GATA3 (GATA binding protein 3)
Diseases named in the same sentence as GATA3 in open-access papers (continued):
Sharing a sentence is not in itself a finding about the gene and the disease.
breast carcinoma (continued). "Next we analyzed CK7 and GATA3 expression among the different histologic types of breast cancer." (PMID 31718619, 2019). "Contractional reports on GATA3 for breast cancer are still available." (PMID 30872657, 2019). "GATA3 has been already used as a specific marker to identify breast cancer metastases." (PMID 30819139, 2019). "Since there are no systematic clinicopathological studies on CK7 and GATA3 negative breast tumors and limited studies characterizing the prognostic utility of GATA3 expression in breast cancer, the current study provided detailed information that is lacking in the literature." (PMID 31718619, 2019). "In breast cancer, only GATA3 could be considered a validated prognosis marker compared with the other GATA family members according to our results." (PMID 30872657, 2019). "AI therapy produces a greater reduction in the Ki-67 proliferation marker in patients who have a GATA3 mutation than in those who do not, which demonstrates that a GATA3 mutation indicates a breast cancer that is sensitive to endocrine therapy." (PMID 31281796, 2019). "Recent studies demonstrated that GATA3 suppressed breast cancer dissemination from the primary site by inhibiting epithelial-to-mesenchymal transition (EMT) and alterations of the tumor microenvironment, such as angiogenesis, collagen remodeling, and proteolysis 9-11." (PMID 31754326, 2019). "GATA3 has been shown to be associated with the luminal subtype of breast cancer, whereas 88% of estrogen receptor (ER)-negative tumors retained GATA3 expression." (PMID 31718619, 2019). "However, more investigations need to be applied to fully reveal the role of GATA3 in breast cancer for further translational study." (PMID 30872657, 2019). "As opposed to CK7 negative tumors, GATA3 negative breast cancer has gained more attention from both diagnostic pathologists and cancer biologists." (PMID 31718619, 2019). "Our findings expand our current knowledge on Notch3 and GATA-3's roles in breast cancer metastasis." (PMID 30100605, 2018). "We therefore determined expression of Notch3 and GATA-3 in tissue samples from breast cancer patients with immunohistochemistry (IHC) and explored their possible relationship with progesterone receptor (PR) and ER statuses, as well as their associations with other clinicopathologic features." (PMID 30100605, 2018). "Of those, FOXA1, ESR1 and GATA3 are not only reported as co-expressed and co-localized in breast cancer cells, but there is even strong evidence suggesting they might form an enhanceosome that regulates many genes involved in the ER signaling cascade." (PMID 29741575, 2018). "These tests can be completed with CDX2 and CK19 for upper gastrointestinal tract, biliary ducts and pancreas, thyroglobulin for thyroid adenocarcinoma, NY-BR-1 and GATA-3 for female breast cancer, Mel-A, S100 and HMB45 for melanoma, and vimentin and Mel-A for kidney and adrenal gland tumors." (PMID 29116378, 2018). "Due to the important roles of Notch3 and GATA-3 as epithelial phenotype markers of breast cancer, we hypothesized that the Notch3/GATA-3 axis modulates the expression of EMT markers." (PMID 30100605, 2018). "Low levels of GATA3 in primary breast cancers correlate with a worse prognosis." (PMID 30218063, 2018). "Similarly, in breast cancer, miR-29b has been shown to decrease metastasis following stimulation by GATA3, through targeting of regulators of angiogenesis, collagen remodelling and proteolysis." (PMID 30323900, 2018). "Moreover, the expression of NY-BR-1 and GATA-3 seemed the most effective for labelling male breast cancer in primary and metastatic setting." (PMID 29116378, 2018). "Furthermore, FOXA1, GATA3, ESR1 and SPDEF are reported as master regulators in FGFR2 signaling and breast cancer risk in ER+ cells." (PMID 29741575, 2018).
breast carcinoma (continued). "Thus, correction of mutant GATA3 back to wild type impaired estrogen-dependent growth of MCF-7 breast cancer cells in vivo, and knock-in mutant GATA3 was sufficient to confer the ability of CAMA1 cells to grow as xenografts in immunocompromised mice." (PMID 29262572, 2017). "GATA3 is involved in breast cancer progression and metastasis." (PMID 28683819, 2017). "However, even at the gene level, the connection between GATA3 expression and survival of breast cancer patients exists." (PMID 28394898, 2017). "GATA3 gene, on the other hand, has been extensively studied in breast cancers." (PMID 28966727, 2017). "Studies using human breast cancer cell lines show that Gata3 co-regulates certain genes with the estrogen receptor alpha (ERα) and that there may be reciprocal regulation between Gata3 and ERα." (PMID 29262572, 2017). "An early, developmental role for GATA3 mutation is not addressed by our cancer cell line model, but an early role does not necessarily preclude a later impact of these mutations on breast cancer phenotypes and outcomes." (PMID 29262572, 2017). "For ETV6, expression of this gene is positively associated with GATA3 in B-ALL only, and with the opposite direction in all other types of leukemia, breast cancer as well as the healthy bone marrow, indicating its specific role on B-ALL leukemogenesis with GATA3 regulation." (PMID 28415601, 2017). "High GATA3 expression may predict TTP in breast cancer, and such patients may show better clinicopathological features." (PMID 28394898, 2017). "In patients with both a primary invasive EMPD and another type of tumor (particularly urothelial and breast carcinoma), the differential diagnosis for a metastatic tumor with positive GATA3 staining should also include metastatic primary EMPDs in the list of differential diagnosis." (PMID 28693610, 2017). "However, until now, no meta-analyses have been performed to evaluate the prognostic value of GATA3 protein expression in breast cancer patients." (PMID 28394898, 2017). "In GOBO analysis, the expression of GATA3 in luminal-like was significantly higher than basal-A or basal-B subtypes of breast cancer, and the hormone receptor (HR) sensitive subtype also expressed higher level of GATA3 than TN (triple-negative) and Her-2 clinical subtypes." (PMID 28423734, 2017). "Also, enhanceosome comprising ER, FOXA1, and GATA3 was found to be sufficient to restore estrogen responsiveness in ER− breast cancer cells." (PMID 28345661, 2017). "General patterns to emerge from these studies include that estrogen receptor (ER)-positive primary breast cancer has a characteristic “luminal” transcriptional profile with frequent somatic mutations activating PI3K-AKT signaling and inactivating GATA3 and the JUN kinase pathway." (PMID 28810143, 2017). "Effect of GATA3 protein expression level on survival and pathological features of breast cancer." (PMID 28394898, 2017). "We think that under conditions of FoxM1 over-expression there is a gain-of-function for Rb (and Rb family proteins) in which it participates in development/maintenance of poorly differentiated breast cancer cells by inhibiting expression of differentiation genes, such as GATA3 and FoxA1." (PMID 28387346, 2017). "Here, using gene editing, we have created two sets of isogenic human luminal breast cancer cell lines with and without a hotspot truncating GATA3 mutation." (PMID 29262572, 2017). "Moreover, in human luminal breast cancer, GATA3 - which works by regulating miRNA-29b expression - emerged as a strong predictor of clinical outcome." (PMID 28423652, 2017). "We next assessed the prognostic effect of GATA3 in breast cancer." (PMID 28423734, 2017).
breast carcinoma (continued). "Recent data from the METABRIC project show improved breast cancer-specific survival for patients with ER+ tumors with GATA3 mutations, although this conclusion is not universally supported by mutation prevalence in metastatic breast cancer." (PMID 29262572, 2017). "Some of the breast cancer-associated truncating mutations cluster in the same region as mutations in the HDR syndrome (hypoparathyroidism, sensorineural deafness, and renal insufficiency), an autosomal dominant disorder ascribed to Gata3 haploinsufficiency." (PMID 29262572, 2017). "Unlike the association of GATA3 with breast cancer, the TFs identified by TENET in prostate cancer have not been well studied." (PMID 27833659, 2016). "Recent studies have begun to address the role of GATA3 in breast cancer." (PMID 27588951, 2016). "Moreover, a transcription factor GATA3 is found to promote miR-29b expression and suppress metastasis of breast cancer by inducing miR-29b." (PMID 27391030, 2016). "We have identified 36 TFs whose regulons are significantly enriched for genes associated with breast cancer risk loci (termed “risk TFs”), and four of these risk TFs (ESR1, FOXA1, GATA3 and SPDEF) have been identified as MRs of FGFR2-mediated risk in breast cancer." (PMID 27997592, 2016). "The role of GATA3 in breast cancer as a tumor suppressor has been established." (PMID 27454576, 2016). "Lack of GATA3 has been linked to cancerogenesis, as absence of GATA3 expression was associated with poor prognosis and undifferentiated tumors in breast cancer." (PMID 27658391, 2016). "Recently, GATA-3 has been shown to be a sensitive marker for breast cancer." (PMID 27337944, 2016). "The biochemical and functional interaction of GATA3 with histone methyltransferases may explain the changes of active histone modifications and altered enhancer accessibility in breast cancer cells depleted of GATA3." (PMID 27588951, 2016). "Importantly, our findings challenge the view that GATA3 only acts as a tumour suppressor that is downregulated or inactivated in breast cancer." (PMID 27588951, 2016). "This is in line with murine breast cancer, where lack of GATA3 is associated with undifferentiated tumors." (PMID 27658391, 2016). "In addition, expression of GATA3 inhibits breast cancer metastasis by driving invasive cancer cells to undergo MET." (PMID 27556500, 2016). "Hence, the distinctive effects of GATA3-ext are recapitulated in an independent breast cancer patient cohort." (PMID 27588951, 2016). "Importantly, the expression levels of the GATA3 proteins were in the physiological range of endogenous GATA3 observed in various other breast cancer cell lines." (PMID 27588951, 2016). "Therefore, we investigated the enhancer to gene links identified above for GATA3 using publicly available ChIP-seq data from a breast cancer cell line." (PMID 27833659, 2016). "On the other hand, GATA3, the low expression of which has been linked to the malignant progression of breast cancers, has been shown to negatively regulate LY6E expression in breast cancer cells." (PMID 27589564, 2016). "Recent studies have identified several genes that under long-range regulation during breast cancer progression, including those encoding transcription factors such as ER, PR, AP1, AP2, FoxA1, GATA3, architectural components such as cohesion and SATB1, coactivators such as p300/CBP and SRC1-3." (PMID 26355959, 2015). "Collectively, these data suggest a menopausal status-dependent role for GATA3 in breast cancer." (PMID 26251034, 2015).
breast carcinoma (continued). "Luminal A breast cancer is the most common subtype, and it also features high expression of genes typically expressed in the luminal epithelium lining in the mammary ducts, such as GATA3, FOXA1, and BCL-2 and low expression of cell proliferation-related genes." (PMID 26561834, 2015). "In addition, miR-29b suppresses metastasis by targeting GATA3, which promotes epithelial-mesenchymal transition in breast cancer." (PMID 26155940, 2015). "Interestingly, recent studies have demonstrated that basal-like breast cancer pathogenesis can be inhibited by the repressive activity of Gata-3 on FOXC1 expression and by the silencing activity of EZH2." (PMID 25962646, 2015). "We tested this on the breast cancer cell line MCF7 for which sequence data from both input material as well as multiple ChIPseq experiments for a number of DNA-associated proteins (ER, EGR1, GATA3, CTCF, MAX, and EP300) are available." (PMID 25887352, 2015). "GATA3 is a sensitive and specific marker for diagnosis of breast carcinomas." (PMID 26408025, 2015). "Furthermore, expression of GATA3 and methylation of GATA-containing enhancer probes were co-linked to breast cancer subtypes." (PMID 25994056, 2015). "Moreover, FOXA1, an effector of PPARγ (Varley etal., 2008) and a co-factor of GATA3 in luminal breast cancer (Kong etal., 2011), is a significant co-regulator of both GATA3 and PPARγ in the inferred network." (PMID 25979476, 2015). "This occured despite the importance of FOXA1 in process involved in cancer development: it forms a strong network with ER- α (estrogen receptor-alpha) and GATA-3 (GATA binding protein 3) and controls the gene expression pattern in luminal subtype A breast cancers." (PMID 26537518, 2015). "The induction of isoform 2 following miR-221 overexpression may be additionally controlled through the positive transcription regulator GATA3 (GATA binding protein 3) that is often overexpressed in breast cancer cells." (PMID 25797271, 2015). "In addition, GATA3 has been shown to be necessary for estradiol stimulation of breast cancer cells and more recently, modulate ERα access to enhancer regions." (PMID 25996148, 2015). "Further insight into the role of GATA3 in coordinating cell cycle progression may contribute to clarify its role in breast cancer." (PMID 25479686, 2014). "For example, GATA3 may promote differentiation, suppress metastasis and alter the tumor microenvironment in breast cancer by inducing miR-29b expression." (PMID 24748983, 2014). "We postulated that various molecular pathways are altered following GATA3 overexpression in luminal breast cancer, which may promote cancer progression." (PMID 25410484, 2014). "In terms of mammary epithelial cell biology, GATA3 is thought to inhibit breast cancer metastasis." (PMID 24426833, 2014). "In breast cancer cells, GATA3 and EZH2 are functionally antagonistic, suggesting that similar interplay between these two factors may also exist in myeloma." (PMID 25188243, 2014). "Nevertheless, we could reach the ERα low/GATA3 low state through a specific perturbation in ERα-positive breast cancer cell lines (compare protein levels at 0 and 48 h in the GATA3 depletion experiments)." (PMID 24792166, 2014). "To determine whether GATA3 protein turnover is regulated in a similar, proteasome-dependent manner in breast cancer, we treated cells with cycloheximide and a proteasome inhibitor, MG132." (PMID 24758297, 2014). "As a result, the functional significance of the correlation between ERα and GATA3 expression in breast cancer cell lines or in normal mammary gland development remains unclear." (PMID 24792166, 2014). "Clustering of patients bearing TAD mutations with BLBC patients may result from reduced activity on target genes mimicking the phenotype of GATA3-low breast cancer, while an altogether divergent and discrete signature characterizes patients with DBD mutations." (PMID 25410484, 2014).
breast carcinoma (continued). "Likewise, GATA3 reconstitution in transgenic animal models suppresses the dissemination of breast cancer." (PMID 24792166, 2014). "GATA3 was identified in the luminal cells of mammary ducts and the body cells of terminal end buds, suggesting that GATA3 actively maintains luminal epithelial differentiation in the adult mammary gland, which suggests important implications in the pathogenesis of breast cancer." (PMID 24748983, 2014). "Thus, the activity of GATA3 in ER-, basal-like breast cancer (BLBC), has been largely attributed to negative regulation of genes associated with invasion and de-differentiation." (PMID 25410484, 2014). "Since previous studies have shown GATA3 26S proteasome-mediated degradation in immune system cells, we hypothesized that the 26S proteasome could be involved in MPA-mediated GATA3 degradation in breast cancer cells." (PMID 25479686, 2014). "ER-α66 is often co-expressed with GATA3 in breast tumors and breast cancer cell lines." (PMID 24558373, 2014). "Indeed, previous molecular-level studies indicated that ERα and GATA3 constitute a transcriptional regulatory network in ERα-positive breast cancer cell lines." (PMID 24792166, 2014). "Importantly, we demonstrate that GATA3 downregulation is required for progestin-induced upregulation of cyclin A2 and for progestin-induced in vitro and in vivo breast cancer cell growth." (PMID 25479686, 2014). "The expression levels of GATA3 in breast cancer patients are strongly correlated with ERα." (PMID 24792166, 2014). "Low GATA3 expression has also been suggested to correlate with poor prognosis in breast cancer." (PMID 24504018, 2014). "Our findings may enable a better understanding of the roles miRNA variants in GATA3 3′UTR play in its mRNA expression and open up novel possibilities for therapeutic intervention in breast cancer." (PMID 24748983, 2014). "The realisation that the GATA3-miR-29b axis regulates the tumor microenvironment and inhibits metastasis may open up novel possibilities for therapeutic intervention in breast cancer." (PMID 24748983, 2014). "To explore major GATA3-regulated genes which may be involved in breast cancer, we correlated expression levels of the GATA3 target genes with clinical data available from breast cancer patients." (PMID 25410484, 2014). "Finally, we demonstrated that GATA3 downregulation is essential for cyclin A2 upregulation and progestin-driven breast cancer growth." (PMID 25479686, 2014). "Tumor suppressor functions of GATA3 have been demonstrated primarily in basal-like breast cancers." (PMID 25410484, 2014). "In addition to ER alpha, we also identified FOXA1 and GATA3 as the TFs with significantly higher activities in ER+ than in ER- breast cancer samples." (PMID 23885756, 2013). "In molecular terms, less differentiated luminal breast cancers, and thus higher histological grade tumors, are expected to express lower levels of luminal lineage differentiation markers, including estrogen receptor and GATA3." (PMID 24205108, 2013). "In addition, it also detected the activity difference of two other breast cancer associated TFs, FOXA1 and GATA3, in ER+ versus ER- samples." (PMID 23885756, 2013). "More specifically, loss of GATA3 expression does not appear to be a requirement for the establishment of metastatic growth in a majority of luminal breast cancers." (PMID 24205108, 2013). "FOXA1 and GATA3 proteins are expressed in ER-positive luminal breast cancers." (PMID 23192763, 2013). "Several transcription factors, e.g. Gata3 and Klf4, have been identified that could induce E-cadherin expression through binding to E-cadherin promoter in human breast cancer cells." (PMID 23284647, 2012).